SNORD53 (small nucleolar RNA, C/D box 53)
Synonyms: U53; SNORD53A; RNU53
Gene: Small nucleolar RNA gene on chromosome 2 (28,927,067 to 28,927,144, forward strand). Ensembl gene ENSG00000265145.
Gene Ontology:
Biological process: RNA processing
Cellular component: nucleolus
Homologues: Orthologues: chimpanzee SNORD53 (100% identical), macaque SNORD53 (100% identical), rabbit SNORD53 (99% identical), pig SNORD53 (97% identical), guinea pig SNORD53 (96% identical), rat Snord53 (91% identical), mouse Snord53 (88% identical). Paralogues in human: SNORD53B (78% identical), SNORD92 (71% identical).
Diseases named in the same sentence as SNORD53 in open-access papers:
SNORD53 is named in the same sentence as 1 disease in open-access papers, as found by Europe PMC text mining. Sharing a sentence is not in itself a finding about the gene and the disease.
liver cancer (1 paper, 2025). An epithelial or non-epithelial malignant neoplasm that arises from the liver.